CXCL12 (C-X-C motif chemokine ligand 12)
Diseases named in the same sentence as CXCL12 in open-access papers (continued):
Sharing a sentence is not in itself a finding about the gene and the disease.
pulmonary hypertension (15 papers, 2011 to 2025). Increased pressure within the pulmonary circulation due to lung or heart disorder. "CXCL12 belongs to the CXC subfamily of chemokines, and increased blood CXCL12 levels are associated with right ventricular dysfunction in patients with idiopathic pulmonary hypertension." (PMID 33816621, 2021). "Recent work in preclinical models suggests that signalling via the pro-angiogenic and pro-inflammatory cytokine, CXCL12 (SDF-1), plays an important pathogenic role in pulmonary hypertension (PH)." (PMID 25856504, 2015). "In a mouse model of pulmonary hypertension, administration of pravastatin ameliorated hypoxia-induced pulmonary hypertension and was associated with decreased accumulation of bone marrow-derived progenitor cells in the pulmonary artery adventitia and reduced plasma levels of CXCL12." (PMID 23369699, 2012). "The neutralization effect of CXCL12 can reduce the infiltration of pulmonary macrophages, so as to improve pulmonary hypertension in rats." (PMID 33816621, 2021). "LIT-927 is the first locally and orally active CXCL12 chemokine-neutralizing molecule (neutraligand) shown to display anti-inflammatory effects in vivo, demonstrated in two murine models mimicking allergic airway hypereosinophilia and pulmonary arterial hypertension, respectively." (PMID 34744730, 2021). "CXCR4 is the receptor for chemokine CXCL12 and reportedly plays an important role in systemic vascular repair and remodeling, but the role of CXCR4 in development of pulmonary hypertension and vascular remodeling has not been fully understood." (PMID 21294880, 2011).
Cognitive impairment (12 papers, 2015 to 2025). Abnormal cognition is characterized by deficits in thinking, reasoning, or remembering. "In the context of cognitive impairment linked to neuropathic pain, CXCL12 facilitates the migration of monocytes into the brain's perivascular spaces, contributing to memory deficits." (PMID 40692664, 2025). "We next sought to determine whether levels of CSF CXCL12 were associated with cognitive impairment in PD." (PMID 34648304, 2021). "Peripheral monocytes and plasma CXCL12 may serve as biomarkers and therapeutic targets for cognitive impairments associated with high-impact chronic pain." (PMID 33391521, 2021). "Among these, Cxcl12 and CxCr4 stand out, as dysregulation of the CXCL12 ligand/CXCR4 receptor axis has been implicated in the cognitive deficits associated with several neurodegenerative diseases." (PMID 40498000, 2025). "Importantly, we found that chronic pain patients also exhibited increased circulating monocytes and plasma CXCL12 correlated with cognitive impairment." (PMID 33391521, 2021). "Additionally, our findings indicate that CXCL12 might be a useful marker to track the severity of cognitive impairment in patients with AD." (PMID 37685973, 2023). "Furthermore, our findings indicate that CXCL12 might be a useful marker for tract severity of cognitive impairment." (PMID 37685973, 2023). "The study examined the interaction between five hub genes (Cxcl10, Gbp2, Cxcl12, Cxcr3, Ifih1) and four distinct immune cell types (M1 macrophages, NK resting cells, memory CD4 T cells, naive CD8 T cells) in mice brain tissues affected by cognitive impairment." (PMID 39286150, 2024). "CXCL12-dependent adult neurogenesis and synaptic plasticity in the dentate gyrus is involved in learning and memory, as wild-type mice treated with a CXCR4 antagonist show cognitive impairment." (PMID 35821178, 2022). "The hippocampal expression of both CXCL12 and CXCR4 were decreased in Tg2576 mice at 6 and 12 months of age as compared to age-matched non-transgenic animals; this was paralleled with cognitive impairment." (PMID 35821178, 2022). "It is noteworthy that we found a negative correlation between CXCL12 and MMSE score in AD patients, which suggests that CXCL12 could be a valuable marker for the assessment of cognitive impairment severity in patients with AD." (PMID 37685973, 2023). "While our current study showed that the SNI-induced pathological changes, including increase in circulating leukocytes, brain PVMs, and gliosis, the elevation of plasma CXCL12 and SNI-induced cognitive impairment were not different between male and female mice." (PMID 33391521, 2021).
endothelial dysfunction (12 papers, 2014 to 2026). In vascular diseases, endothelial dysfunction is a systemic pathological state of the endothelium (the inner lining of blood vessels) and can be broadly defined as an imbalance between vasodilating and vasoconstricting substances produced by (or acting on) the endothelium. "Together, these data suggest that the circulating SASP milieu underlies age-related endothelial dysfunction and its detrimental effects are in part mediated by CXCL12 and largely reversed by senolytic treatment with fisetin." (PMID 40894771, 2025). "Further, we uncover mechansims underlying the circulating SASP milieu- and CXCL12-mediated endothelial dysfunction including NO production, mitochondrial oxidative stress, and endothelial cell trandifferentiation." (PMID 40894771, 2025). "The addition and inhibition of CXCL12 in our plasma exposure experiments supports a causal role for CXCL12 in age-related endothelial dysfunction, as inhibition of CXCL12 in old vehicle plasma improved endothelial responses and adding exogenous CXCL12 to young plasma induced endothelial dysfunction." (PMID 40894771, 2025). "The ability of fisetin to ameliorate CXCL12-driven endothelial dysfunction further underscores its therapeutic potential in mitigating vascular aging." (PMID 40894771, 2025). "This study provides novel mechanistic insight into how senescent endothelial cells and their secretory products—particularily CXCL12—contribute to age-related endothelial dysfunction." (PMID 40894771, 2025). "Given the crucial role of glycolysis in endothelial dysfunction and Eno1's RNA‐binding capability, we selected Eno1 for further investigation to explore the role of lactylation in CXCL12 production." (PMID 40895187, 2025). "The circulating SASP milieu-mediated endothelial dysfunction was largely stimulated by independent effects of CXCL12 via humoral cellular senescence induction, reduced NO production, and stimulated mitochondrial oxidative stress." (PMID 40894771, 2025). "Mechanistically, we uncovered that the circulating SASP milieu and CXCL12 induce cellular senescence, reduce NO production, promote mitochondrial oxidative stress, and stimulate EndoMT to confer endothelial dysfunction." (PMID 40894771, 2025). "ER stress also promotes endothelial dysfunction in DR, and the predominant inducer is chemokine SDF1 (stromal cell-derived factor), also known as CXCL12." (PMID 36016568, 2022). "It is also possible that CXCL12 suppression, in conjunction with altered Ang-2/Ang-1 ratios, collectively contribute to endothelial dysfunction in our model." (PMID 25254971, 2014). "Moreover, the addition of CXCL12 to old fisetin plasma recapitulated age-related endothelial dysfunction, indicating that senolytic treatment with fisetin mitigated circulating SASP milieu-related endothelial dysfunction, in part, by targeting CXCL12." (PMID 40894771, 2025). "Circulating SASP milieu- and CXCL12-induced endothelial dysfunction." (PMID 40894771, 2025). "Given that CXCL12 has been implicated in inflammatory and cellular senescence-related pathways, its effects as a circulating SASP factor provide mechanistic insight into how endothelial dysfunction develops with aging." (PMID 40894771, 2025). "To determine the mechanistic role of CXCL12 in circulating SASP milieu-mediated endothelial dysfunction, we added back recombinant mouse CXCL12 to old fisetin plasma such that the average concentrations of plasma CXCL12 was similar to that of old vehicle plasma." (PMID 40894771, 2025). "Finally, we revealed a causal role of the circulating SASP milieu in inducing age-related endothelial dysfunction mediated, in part, by the elevated concentration of CXCL12." (PMID 40894771, 2025).
head and neck squamous cell carcinoma (12 papers, 2009 to 2025). A squamous cell carcinoma that arises from any of the following anatomic sites: lip and oral cavity, nasal cavity, paranasal sinuses, pharynx, larynx, and salivary glands. "Publicly available single‐cell RNA‐sequencing (RNA‐seq) datasets were used to analyze CXCL12 expression in head and neck squamous cell carcinomas (HNSCC)." (PMID 36300800, 2023). "In head and neck squamous cell carcinomas (HNSCC), as in many other cancer types, the CXCL12/CXCR4 axis is involved in metastatic dissemination." (PMID 32296435, 2020).
ovarian tumors (12 papers, 2007 to 2023). "Hypoxia has also been shown to induce CXCL12 expression by primary human ovarian tumour cells where hypoxia-inducible factor-1 is the central mediator." (PMID 22415233, 2012). "CXCL12 regulation within breast and ovarian tumours has been attributed to oestradiol, which activates oestrogen receptors and induces the production of CXCL12 by tumour cells." (PMID 22415233, 2012). "Using tissue microarray technology (TMA) we analysed a large cohort of ovarian tumour samples from 289 patients for CXCL12 and CXCR4 expression." (PMID 22415233, 2012). "The chemokines, including CXCL12, are produced locally in ovarian tumors and contribute to tumor microenvironment." (PMID 21750716, 2011). "Hypoxia induces the expression of CXCL12 in primary human ovarian tumor cells." (PMID 34950205, 2021). "Expression of CXCL12 by ovarian tumours was shown to be an independent prognostic marker (P=0.016)." (PMID 22415233, 2012). "Furthermore, CXCL12 expression was an independent predictor of poor survival and was equally expressed by all ovarian tumour types." (PMID 22415233, 2012). "The relationship between CXCL12 and CXCR4 expression within ovarian tumours and standard clinicopathological variables was measured using the Pearson's χ2-test." (PMID 22415233, 2012).
renal carcinoma (12 papers, 2009 to 2022). A carcinoma arising from the epithelium of the renal parenchyma or the renal pelvis. "CXCR4 and CXCL-12 responses to cisplatin were monitored for 21 days in renal cancer organoid modeling in alginate." (PMID 36551144, 2022). "In addition, CXCL12 induced redistribution of various integrins between cell surface and intracellular compartments in renal carcinoma cells." (PMID 22253872, 2012). "Thus, regulation of the CXCL12, CXCR4, and CXCR7 genes appears to be of minor importance for epithelialization in forming nephrons but might be relevant in diseases including renal carcinoma and fibrosis that are associated with epithelial-to-mesenchymal transition." (PMID 22880115, 2012). "SN12C and A498 cells migrated toward CXCL12 and CXCL11; the migration toward CXCL12 was inhibited by anti-CXCR4 and Peptide R, whereas CXCL11-induced migration was inhibited by anti-CXCR7 demonstrating that both chemokine receptors affected migration in renal cancer cells." (PMID 24991762, 2014). "To address the effects of NFs on cytokines potentially involved in renal cancer progression, we examined, with ELISA assay, some relevant cytokines, such as IL6, VEGF, CXCL12, and IL1β, in medium with the presence or absence of NF-CM after 72 h." (PMID 31636361, 2020).
type 1 diabetes (12 papers, 2015 to 2026). "CXCL12 is a key mediator of repair in many disease models, such as islet β cell loss in type 1 diabetes, intravascular injury, vascular obstruction, and ischemic acute renal failure." (PMID 38716725, 2024). "For example, Cxcl12 supports β cell survival in a mouse model of type 1 diabetes and recruits macrophages to promote β cell regeneration after damage, while IL-6 has been shown to directly enhance insulin secretion." (PMID 38885342, 2024). "In view of its ability to stimulate the regeneration, proliferation, and survival of β-cells, as well as its capacity to sustain local immune-isolation, CXCL12 has been considered in approaches aimed at attenuating type 1 diabetes." (PMID 26300887, 2015). "Moreover, the shared enrichment of ICAM1 and CXCL12 in Type 1 diabetes pathways suggests that these genes may exacerbate the onset and progression of PD in diabetic patients." (PMID 41377896, 2025). "Aside from increasing D28K expression, Isx9 also induced the expression of cytoprotective molecules such as CXCL12 and CXR4, which have the ability to stimulate regeneration and survival of β-cells in type 1 diabetes." (PMID 30150605, 2018).
Hypertension (11 papers, 2008 to 2024). The presence of chronic increased pressure in the systemic arterial system. "Meanwhile, we found that C5AR1, CCL4L2, CCL4, CCL20, CD163, CXCL3, and CXCL12 were only expressed in disease a, suggesting the recruitment of inflammatory factors and promotion of the inflammatory response were both more obvious in hypertension-induced AD." (PMID 35800890, 2022).
neuropathy (11 papers, 2007 to 2023). A disorder affecting the nervous system that manifests with pain, tingling, numbness, and/or muscle weakness. "Consistently, CXCR4 receptors have been observed both in DRG and SC, and implicated in CXCL12-mediated pain regulation after neuropathy." (PMID 24735601, 2014). "Specifically, these DEGs were associated with neuropathy-related pathways, such as GABRD, GABRP, TBX1, and SOX10, and inflammatory responses such as CXCL3, CXCL12, TNF, and IL6." (PMID 36147849, 2022). "Other studies have confirmed the role of chemokine CXCL12 and chemokine CX3CL1 signaling in oxaliplatin-induced neuropathy." (PMID 37834455, 2023). "Recent studies on the pathophysiological mechanisms of CXCL12/CXCR4 axis in the pathogenesis of pain by various nerve injury and neuropathy models, including diabetic neuropathy, demonstrate the axis as a promising pharmacological target." (PMID 32019145, 2020).
osteoporosis (11 papers, 2012 to 2025). A condition of reduced bone mass, with decreased cortical thickness and a decrease in the number and size of the trabeculae of cancellous bone (but normal chemical composition), resulting in increased fracture incidence. "Estrogen deficiency induces miR-29a loss, which causes RANKL and CXCL12 overproduction to exaggerate osteoclastic resorption and ultimately provokes osteoporosis." (PMID 31543513, 2019). "Aging-associated degenerative diseases such as osteoporosis were linked to dysfunctional stem cell differentiation and a decline in the regenerative capacity of musculoskeletal stem cells, resulting from the secretion of pro-inflammatory cytokines such as CXCL12." (PMID 35347083, 2022). "MiR-29a represses osteoclast formation and protects against osteoporosis by regulating P300/CBP-associated factor (PCAF)-mediated RANKL and C-X-C motif chemokine ligand 12 (CXCL12)." (PMID 36831000, 2023). "As a consequence, the altered expression of miR-29a triggered the overproduction of the receptor activator of nuclear factor kappa-B ligand (RANKL) and C-X-C motif chemokine ligand 12 (CXCL12) and enhanced osteoclastic resorption and osteoporosis." (PMID 35011442, 2021). "Taken together, miR-29a signaling in osteogenic cells protects bone tissue from osteoporosis through repressing osteoclast regulators RANKL and CXCL12 to reduce osteoclastogenic differentiation." (PMID 31543513, 2019).
renal fibrosis (11 papers, 2014 to 2026). A final common manifestation of a wide variety of chronic kidney diseases characterized by glomerulosclerosis and tubulointerstitial fibrosis. "Early changes (increases) in MMP-1 concentrations post-CXCL12 injection may play a role in the attenuation of renal fibrosis with CXCL12 treatment, but our small sample size (n = 1) precludes us from making this conclusion." (PMID 33748219, 2021). "A proposed mechanism for the observed attenuation in I/R-induced renal fibrosis and collagen fiber widening may be early, short-term CXCL12 treatment effects on collagenases and collagen cross-linking enzymes as suggested by our small study findings." (PMID 33748219, 2021). "BM-mobilized macrophages and fibrotic cells express CXCR4 and infiltrated CXCL12-enriched tissue; however, we did not identify the type of cell that contributes to renal fibrosis in UUO kidney." (PMID 30818366, 2019).
rhabdomyosarcoma (11 papers, 2011 to 2024). A rare aggressive malignant mesenchymal neoplasm arising from skeletal muscle. "In a study investigating the CXCL12/CXCR4/ACKR3 axis in rhabdomyosarcomas, ACKR3 promoter activity was shown to depend on an NF-κB binding site." (PMID 35674847, 2022). "In rhabdomyosarcoma, the CXCL12/CXCR4 axis is crucial for the metastatic process and high CXCR4 expression is associated with poor outcome." (PMID 34440844, 2021). "Previous studies have shown that CXCR4 correlates with the expression of the angiogenic factor VEGF in STSs, and that the CXCR4/CXCL12 complex may participate in tumor dissemination and metastasis in rhabdomyosarcoma cell lines." (PMID 38893721, 2024). "Moreover, CXCR7 has been reported to mediate CXCL12 chemotaxis in T cells and rhabdomyosarcoma cells, and to promote hepatocellular carcinoma invasion in vitro." (PMID 22152016, 2011). "Consistent with these previous findings, our results for MDX1338, a fully human mAb blocking the CXCR4/CXCL12 axis, show that this mAb can efficiently decrease the migration and invasion indices of metastatic RH30 rhabdomyosarcoma cells in vitro." (PMID 31428099, 2019). "Binding of CXCL12 or interferon-inducible T-cell alpha chemoattractant (I-TAC/CXCL11), the other known CXCR7 ligand, to CXCR7 activates PI3K and MAPK signaling in astrocytes, Schwann cells, gliomas, rhabdomyosarcoma, and pancreatic cancer cells." (PMID 22152016, 2011).
cardiac hypertrophy (10 papers, 2015 to 2023). "Here, we show for the first time a prominent role of SMC derived CXCL12 for vessel development and maturation, progression of cardiac hypertrophy, and tissue homeostasis of CD206 macrophages." (PMID 34072818, 2021). "Our data suggest a critical role of smooth muscle-specific CXCL12 in arterial development, vessel maturation, and cardiac hypertrophy." (PMID 34072818, 2021). "In summary, we provide completely novel data signifying the cell-specific role of smooth muscle-derived CXCL12 in cardiovascular development, arterial maturation, and progression to cardiac hypertrophy." (PMID 34072818, 2021). "In this model, isoproterenol-induced cardiac hypertrophy was related to worsening of cardiac function, increased fibrosis, and apoptosis, implicating CXCL12/CXCR4 signaling in the regulation of cardiac hypertrophy, tissue remodeling, and apoptosis." (PMID 34072818, 2021). "However, there is only limited evidence showing a substantial role of CXCL12 in the progression of cardiac hypertrophy." (PMID 34072818, 2021). "In our model, lack of SMC-derived CXCL12 led to severe cardiac hypertrophy associated with progressive fibrosis and apoptosis." (PMID 34072818, 2021). "While cKO of CXCL12 in SMCs lead to decreased expression of its corresponding receptor CXCR7 in endothelial cells, treatment with a CXCR7 agonist attenuated cardiac hypertrophy and restored cardiac function in cKO mice." (PMID 34072818, 2021). "The second corresponding receptor for CXCL12, CXCR7, is also known to be involved in cardiac hypertrophy." (PMID 34072818, 2021). "An additional chemokine involved in cardiac hypertrophy and remodeling is CXCL12, also known as stromal cell-derived factor 1 (SDF-1)." (PMID 27242392, 2016).
glomerulosclerosis (10 papers, 2015 to 2025). A hardening of the kidney glomerulus caused by scarring of the blood vessels. "In addition, CXCL12, a chemokine produced by podocytes, has also been reported to cause proteinuria and glomerulosclerosis in diabetic mice." (PMID 39337537, 2024). "NOX-A12, a CXCL12-specific inhibitor, can improve proteinuria and glomerulosclerosis in db/db mice." (PMID 39337537, 2024).